HTT (huntingtin)
Diseases named in the same sentence as HTT in open-access papers (continued):
Sharing a sentence is not in itself a finding about the gene and the disease.
Huntington disease (continued). "Huntington’s disease (HD) is a rare, progressive ND caused by an autosomal-dominant mutation in the huntingtin (HTT) gene, leading to severe neuronal loss in the brain and resulting in debilitating motor, cognitive, and psychiatric symptoms." (PMID 40001897, 2025). "The mutant form of HTT (mHTT), characterized by an abnormal polyglutamine (polyQ) expansion in its N-terminal region, is the causative agent of Huntington’s disease (HD), a progressive neurodegenerative disorder." (PMID 41303392, 2025). "Huntington’s disease (HD) is an autosomal dominant, progressive neurodegenerative disorder caused by a cytosine-adenine-guanine trinucleotide repeat expansion in the huntingtin (HTT) gene." (PMID 41480464, 2025). "Huntington’s disease (HD) is a neurodegenerative disorder caused by CAG repeat expansions in the huntingtin gene (HTT)." (PMID 40356918, 2025). "Huntington’s disease (HD) is a dominantly inherited fatal neurodegenerative disease caused by CAG repeat expansion in the HTT gene, encoding an extended polyglutamine (polyQ) sequence in mutant HTT (mHTT)." (PMID 40777236, 2025). "Huntington disease (HD) is a neurodegenerative disease caused by a polyglutamine expansion (polyQ) in the Huntingtin protein (muHTT), which makes it prone to misfolding and aggregation." (PMID 41145409, 2025). "Huntington’s disease is a rare neurodegenerative disorder caused by an autosomal dominantly-inherited CAG-trinucleotide repeat-expansion encoding for glutamine in the huntingtin (HTT) gene, leading to protein misfolding and aggregation of aberrant proteins." (PMID 38463392, 2024). "Aggregates formed by the mutant huntingtin protein associated with Huntington’s disease are typically found both in the nucleus and the cytoplasm." (PMID 38899618, 2024). "Huntington’s disease (HD) is an inherited neurodegenerative disorder caused by the abnormal expansion of CAG repeats in the huntingtin gene (HTT), which is located on chromosome 4p16." (PMID 38612657, 2024). "Huntington’s disease (HD) is a genetically inherited dominant neurodegenerative disorder caused by expansion of a CAG repeat sequence in the coding sequence of huntingtin protein (HTT)." (PMID 38565397, 2024). "Huntington's disease is caused by an extra-long CAG sequence in the huntingtin gene which increases in length with age." (PMID 38387080, 2024). "The cause of Huntington's disease is the repeat expansion of CAG in the mutant HTT gene, which leads to polyglutamine tract enlargement in the N‐terminal of the Huntington (Htt) protein." (PMID 36237157, 2024). "Huntington’s disease (HD) is an autosomal dominant neurodegenerative disease caused by an expansion of the CAG trinucleotide repeat in exon 1 of the huntingtin (HTT) gene." (PMID 38666850, 2024). "Huntington’s disease is an inherited neurodegenerative disease caused by a mutation in the gene encoding the huntingtin protein, which leads to its accumulation and neuronal death." (PMID 38666850, 2024). "Mutant variants (mHTT) generated by expansion of CAG repeats in exon 1 of the HTT gene located on chromosome 4 are the cause of Huntington's disease (HD)." (PMID 39465903, 2024). "The accumulation of mutant huntingtin protein aggregates in neurons is a pathological hallmark of Huntington’s disease (HD)." (PMID 39226105, 2024). "Huntington's disease (HD) is a progressive neurodegenerative disorder caused by abnormal CAG repeat expansions in the huntingtin gene." (PMID 39239850, 2024). "These ASOs target specific polymorphisms of the mutant mRNA of the Huntingtin (HTT) gene, in adult patients (25–65 years old) with early manifest Huntington's disease." (PMID 39526481, 2024). "Huntington’s disease (HD) is a debilitating neurodegenerative genetic disorder caused by an expanded polyglutamine-encoding CAG repeat in the huntingtin gene (HTT)." (PMID 38776957, 2024).
Huntington disease (continued). "Huntington’s disease (HD) is marked by a CAG-repeat expansion in the huntingtin gene that causes neuronal dysfunction and loss, affecting mainly the striatum and the cortex." (PMID 38627751, 2024). "Huntington’s disease (HD) is a progressive neurodegenerative disease caused by a CAG trinucleotide expansion in the huntingtin gene." (PMID 38841617, 2024). "Huntington's disease (HD) is an inherited neurodegenerative disorder caused by an expanded CAG repeat in the coding sequence of huntingtin protein." (PMID 38840253, 2024). "The abnormal accumulation of mutated huntingtin protein, which causes neuronal dysfunction and degeneration, is the hallmark of Huntington’s disease." (PMID 38375509, 2024). "Individuals with ≥40 cytosine-adenine-guanine repeats on the interesting transcript 15 gene develop Huntington's disease due to a mutated huntingtin protein." (PMID 38938620, 2024). "In Huntington’s disease (HD), aberrant processing of huntingtin (HTT) mRNA produces HTT1a transcripts that encode the pathogenic HTT exon 1 protein." (PMID 39394467, 2024). "Huntington’s Disease (HD) is caused by an expansion of CAG codons within exon 1 of the huntingtin (HTT) gene." (PMID 38921455, 2024). "Mutations in particular genes, such as the APP, PSEN1, and PSEN2 genes associated with AD and HTT in Huntington’s disease, contribute to familial variants of these NDs, and genetic factors play a major role in these cases." (PMID 38612804, 2024). "Huntington's disease (HD) is a progressive neurodegenerative disorder caused by CAG trinucleotide repeat expansions in exon 1 of the HTT gene." (PMID 38267530, 2024). "Huntington’s disease (HD) is a progressive genetic disorder caused by the accumulation of mutant huntingtin (mHTT) protein, leading to motor, cognitive and psychiatric disturbances." (PMID 39451571, 2024). "Huntington's disease (HD) is a neurological disorder caused by a CAG expansion in the Huntingtin gene (HTT)." (PMID 38863004, 2024). "Huntington’s disease (HD) is a neurodegenerative disorder caused by the expansion of the CAG repeat in exon 1 of the HTT gene, leading to the formation of a toxic variant of the huntingtin protein." (PMID 39519046, 2024). "Huntington’s Disease (HD) is caused by a trinucleotide repeat in exon 1 of the Huntingtin (HTT) gene." (PMID 38510848, 2024). "Huntington’s disease (HD) is a neurodegenerative disease caused by the CAG amplification of the Huntington protein (HTT) gene." (PMID 38515621, 2024). "Huntington’s disease (HD) is primarily caused by the aberrant aggregation of the N-terminal exon 1 fragment of mutant huntingtin protein (mHttex1) with expanded polyglutamine (polyQ) repeats in neurons." (PMID 39845903, 2024). "Huntington’s Disease results in the production of a mutant HTT protein that causes an increased presence of pro-inflammatory cytokines that are able to induce caspases and the production of free radicals." (PMID 38921455, 2024). "Huntington’s disease (HD) is a hereditary neurodegenerative disorder caused by a CAG tract expansion in the huntingtin gene (HTT)." (PMID 39519337, 2024). "The disease-causing mutation in Huntington disease (HD) is a CAG trinucleotide expansion in the huntingtin (HTT) gene." (PMID 38459427, 2024). "Huntington’s disease is an inherited neurodegenerative disorder caused by a CAG repeat expansion that encodes a polyglutamine tract in the huntingtin (HTT) protein." (PMID 39713241, 2024). "For example, Huntington’s disease is caused by elongated repeats of glutamine (polyQ) in the Huntingtin protein that lead to misfolding and aggregation of the protein." (PMID 39146256, 2024). "Huntington’s disease arises from a mutation in the HTT gene, leading to an abnormal expansion of CAG repeats that encode a polyglutamine (polyQ) tract in the huntingtin protein." (PMID 39684324, 2024). "Huntington's disease (HD) is an inherited neurodegenerative disease linked to a CAG repeat expansion at the Huntingtin gene (HTT; MIM:613004)." (PMID 38418081, 2024).
Huntington disease (continued). "Huntington disease (HD) is a dominantly inherited neurodegenerative disorder caused by a CAG expansion on the huntingtin (HTT) gene and is characterized by progressive motor, cognitive, and neuropsychiatric decline." (PMID 38927742, 2024). "Huntington’s disease is a polyglutamine disease caused by mutations in the huntingtin gene and involves abnormal repeats in the glutamine–encoding CAG." (PMID 38525704, 2024). "Huntington’s disease is caused by an abnormal CAG repeat expansion within the huntingtin (Htt) gene, which leads to widespread physiological disruption." (PMID 39161652, 2024). "Huntington’s disease (HD) is a rare neurodegenerative disorder caused by inherited defects in the gene Huntingtin (HTT) encoding for the protein HTT." (PMID 39174523, 2024). "Huntingtin protein, mutated in Huntington’s disease, is implicated in nucleic acid–mediated processes, yet the evidence for direct huntingtin–nucleic acid interaction is limited." (PMID 39028820, 2024). "Huntington's disease is a neurodegenerative disease caused by a repeat expansion in the Huntingtin gene and characterized by the loss of dopamine 2 and dopamine 1 receptor–expressing medium spiny neurons [D2 and D1 medium spiny neurons (MSNs)] of the striatum." (PMID 39500579, 2024). "Huntington’s disease is caused by a mutation in the huntingtin (HTT) gene, which leads to the production of an abnormal form of the huntingtin protein." (PMID 39590469, 2024). "Huntington’s disease is a good example, where the susceptible cells are expressing a mutant form of the huntingtin protein." (PMID 39201726, 2024). "Huntington's disease (HD) is a hereditary neurodegenerative disorder that causes chorea and motor dysfunction due to a mutation in the Huntingtin (HTT) gene." (PMID 39544557, 2024). "Huntington’s Disease (HD) is a neurodegenerative disorder caused by an autosomal-dominant mutation in the huntingtin gene, which manifests with a triad of motor, cognitive and psychiatric declines." (PMID 39200241, 2024). "In the same vein, the pathogenic protein mutant huntingtin, linked to Huntington’s disease, forms aggresomes near the nucleus and is degraded by autophagy." (PMID 38899618, 2024). "Huntington's disease is caused by expanded CAG triplet repeats at the N-terminus of the huntingtin (Htt) gene." (PMID 38739933, 2024). "In Huntington’s disease, a mutation in the huntingtin gene results in the expression of mutant huntingtin protein (mHtt), which has abnormal polyQ expansions." (PMID 38550381, 2024). "Huntington’s disease (HD) is a highly penetrant neurodegenerative disease caused by an autosomal dominantly inherited CAG trinucleotide repeat expansion in the huntingtin gene on chromosome 4." (PMID 39203889, 2024). "For example, mutations in the HTT gene, which encodes a protein called huntingtin, cause Huntington’s disease." (PMID 38340090, 2024). "Pathogenic mutant huntingtin (mHTT) infiltrates the adult Huntington’s disease (HD) brain and impairs fetal corticogenesis." (PMID 38654124, 2024). "Huntington disease (HD) is a neurodegenerative disease caused by the abnormal expansion of a polyglutamine tract resulting from a mutation in the HTT gene." (PMID 38341417, 2024). "In conditions like Huntington’s disease, EVs can carry mutated huntingtin protein, detectable in biofluids such as cerebrospinal fluid (CSF) and blood, aiding in diagnosis." (PMID 39796048, 2024). "Huntington’s disease (HD) is a neurodegenerative disease caused by a CAG trinucleotide repeat increase in the huntingtin gene (HTT)." (PMID 38727281, 2024). "VDAC1 has also been associated with the pathological mechanisms involved in other neurodegenerative diseases, such as Huntington’s disease (HD), a neurodegenerative disorder caused by repeat expansions in the huntingtin (HTT) gene." (PMID 39858428, 2024).
Huntington disease (continued). "The Huntington's disease mutation is a CAG repeat expansion in the huntingtin gene that results in an expanded polyglutamine tract in the huntingtin protein." (PMID 38387080, 2024). "In this study, we investigated the effect of the Huntington’s disease mutation on mutant HTT protein levels as well as the comparative performance of HTRF and MSD assays designed to detect soluble HTT isoforms." (PMID 39713241, 2024). "Huntington’s disease (HD) is a fatal neurodegenerative disorder caused by an expanded CAG tract in the huntingtin (HTT) gene, leading to toxic gains of function." (PMID 39054288, 2024). "Huntington’s disease (HD) is a neurodegenerative disease caused by an expansion of the trinucleotide CAG within exon-1 of the Huntingtin (HTT) gene." (PMID 38459557, 2024). "SPS reduced Htt (huntingtin) gene expression, which has been linked to cerebral ischemia, Huntington’s disease, and Parkinson’s disease." (PMID 39628496, 2024). "Research into one subtype, glutamine synthetase 1 (GS1), has found that the expression of GS1 helps to alleviate the mortality and pathologic defects present in Drosophila flies that present with mutant huntingtin, which is known to cause Huntington’s Disease." (PMID 38921455, 2024). "Expansion of the glutamine tract (poly-Q) in the protein huntingtin (HTT) causes the neurodegenerative disorder Huntington’s disease (HD)." (PMID 39174523, 2024). "Huntington’s disease (HD) is an inherited neurological disease caused by a mutation in the HTT gene." (PMID 39337066, 2024). "Huntington’s disease (HD) is a monogenic neurodegenerative disorder caused by a cytosine–adenine–guanine (CAG) trinucleotide repeat expansion in the HTT gene." (PMID 38931834, 2024). "Huntington’s disease (HD) is a dominant neurological disorder caused by an expanded HTT exon 1 CAG repeat that lengthens huntingtin’s polyglutamine tract." (PMID 38609352, 2024). "Huntington’s disease (HD) is a dominantly inherited autosomal disorder caused by the abnormal expansion of three-base-pair (CAG) repeats in the gene encoding huntingtin (HTT)." (PMID 39022733, 2024). "Huntington’s disease (HD) is an incurable inherited disorder caused by a repeated expansion of glutamines in the huntingtin gene (Htt)." (PMID 38374466, 2024). "Huntington disease (HD) is caused by an expanded polyglutamine mutation in huntingtin (mHTT) that promotes prominent atrophy in the striatum and subsequent psychiatric, cognitive deficits, and choreiform movements." (PMID 38447791, 2024). "Huntington’s disease (HD) is a debilitating neurodegenerative disease caused by a CAG repeat expansion in exon-1 of the huntingtin gene, resulting in the expression of polyglutamine (polyQ) proteins that are prone to aggregate." (PMID 39150509, 2024). "Huntington's disease (HD), a neurodegenerative disorder, is caused by aberrant expansion of polyQ repeat in the N-terminus of the Huntingtin (HTT) protein." (PMID 38224455, 2024). "Huntington’s disease (HD) is characterized by severe neurodegeneration resulting from a mutation in the huntingtin protein (HTT)." (PMID 39574978, 2024). "Huntington’s disease (HD) is a rare genetic neurodegenerative disorder caused by an expansion of CAG repeats in the Huntingtin (HTT) gene." (PMID 39170678, 2024). "Huntington disease (HD) (OMIM 143100) is a neurodegenerative disorder caused by the pathogenic expansion of the CAG trinucleotide in exon one of the huntingtin (HTT) gene." (PMID 38433266, 2024). "Huntington’s disease (HD) is a neurodegenerative genetic disorder caused by an expansion in the CAG repeat tract of the huntingtin (HTT) gene resulting in behavioural, cognitive, and motor defects." (PMID 38776957, 2024). "Huntington's disease (HD) is an inherited neurodegenerative disorder caused by a triple cytosine–adenine–guanine (CAG) repeat expansion in the gene encoding for the Huntingtin (Htt) protein." (PMID 39500579, 2024).
Huntington disease (continued). "DNA mismatch repair (MMR) is thought to contribute to the onset and progression of Huntington disease (HD) by promoting somatic expansion of the pathogenic CAG nucleotide repeat in the huntingtin gene (HTT)." (PMID 38383663, 2024). "In particular, Huntington’s disease (HD) is caused by mutations leading to an abnormal expansion in the polyglutamine (poly-Q) tract of the huntingtin protein (HTT), leading to the formation of inclusion bodies in neurons of affected patients." (PMID 38993838, 2024). "Huntington's Disease (HD) is a fatal, neurodegenerative disease caused by aggregation of the huntingtin protein (htt) with an expanded polyglutamine (polyQ) domain into amyloid fibrils." (PMID 38483973, 2024). "Huntington’s disease (HD) is caused by a polyglutamine expansion of the huntingtin protein, resulting in the formation of polyglutamine aggregates." (PMID 39150509, 2024). "Huntington’s disease (HD) is a dominantly inherited neurodegenerative disorder caused by a CAG repeat expansion in the first exon of the Huntingtin gene (HTT)." (PMID 39170678, 2024). "Huntington’s disease (HD) is a fatal neurodegenerative disorder caused by an expansion of the CAG trinucleotide repeat in the Huntingtin gene (HTT)." (PMID 38459557, 2024). "The pathological huntingtin (HTT) trinucleotide repeat underlying Huntington disease (HD) continues to expand throughout life." (PMID 38749429, 2024). "Huntington’s disease (HD) is a neurodegenerative disease caused by an abnormal expansion of CAG repeats in the huntingtin (Htt) gene." (PMID 38374466, 2024). "HTT is most well known as the gene in which an expansion of a glutamine-coding CAG repeat causes Huntington’s disease (HD), an autosomal dominant, fatal, neurodegenerative disease." (PMID 39054288, 2024). "Comparable associations were made in the context of Huntington’s disease, where ubiquitination of K6 and K9 within huntingtin led to the formation of fewer but larger protein aggregates." (PMID 37273907, 2023). "Huntington’s disease (HD) is caused by a cytosine adenine guanine-repeat expansion in the huntingtin gene." (PMID 37005488, 2023). "Huntington’s disease (HD) is caused by an expansion of a CAG repeat in the gene that encodes the huntingtin protein (HTT)." (PMID 37685866, 2023). "Huntington’s disease (HD) is a chronic inherited neurodegenerative disease caused by CAG trinucleotide repeat expansion in the huntingtin (htt) gene on chromosome 4." (PMID 37351153, 2023). "In the same way, Huntington’s disease is caused by an abnormal expansion of the CAG trinucleotide repeat in the huntingtin gene." (PMID 37760929, 2023). "Huntington’s disease is caused by an unstable expansion of glutamine encoded by the genetic codon CAG within exon 1 of the HTT gene, which encodes the huntingtin protein." (PMID 38249295, 2023). "We therefore tested the unknome gene set for protein quality control phenotypes, using an assay based on aggregation of GFP-tagged polyglutamine, a structure found in mutants of huntingtin that cause Huntington’s disease." (PMID 37552676, 2023). "The Huntington disease (HD) is associated with mutations in the huntingtin protein, which clumps within neurons provoking cell damage and death." (PMID 37223102, 2023). "HD, also referred to as Huntington's chorea, is an inherited neurodegenerative disorder that is associated with an expanded polyglutamine (poly Q) region in the protein encoded by the huntingtin (HTT) gene." (PMID 40224594, 2023). "Huntington’s disease is an autosomal-dominant disease caused by the mutation in the HTT protein, and these mutated proteins form perinuclear cytoplasmic aggregates and intracellular inclusions which are normally removed through the autophagy process." (PMID 37627261, 2023).